CCER2 (coiled-coil glutamate rich protein 2)
Tractability: Antibody: UniProt places it where antibodies can reach, with high confidence; UniProt predicts a signal peptide or a membrane-spanning region; its Gene Ontology location is reachable by antibodies, with medium confidence.
Gene: Protein-coding gene on chromosome 19 (38,908,980 to 38,912,186, reverse strand). Ensembl gene ENSG00000262484.
Subcellular location: Secreted
Gene Ontology:
Cellular component: extracellular region
Genetic constraint (gnomAD): Loss-of-function variants: 21 observed, 23.29 expected, observed/expected ratio (o/e) 0.9, 90% interval 0.64 to 1.3. The upper end of that interval is the gene's LOEUF score, 1.3, which puts it in group 5 of 6, group 1 being the genes least tolerant of losing a copy. Missense variants: 351 observed, 306.23 expected, observed/expected ratio (o/e) 1.15, 90% interval 1.05 to 1.25. Synonymous variants: 140 observed, 123.83 expected, observed/expected ratio (o/e) 1.13, 90% interval 0.99 to 1.3.
Homologues: Orthologues: chimpanzee CCER2 (98% identical), macaque CCER2 (91% identical), dog CCER2 (72% identical), rat Ccer2 (66% identical), pig CCER2 (66% identical), mouse Ccer2 (65% identical), guinea pig CCER2 (57% identical).
Diseases named in the same sentence as CCER2 in open-access papers:
CCER2 is named in the same sentence as 1 disease in open-access papers, as found by Europe PMC text mining. Sharing a sentence is not in itself a finding about the gene and the disease. The quoted sentences say what the papers report.
tumor (1 paper, 2025). "The MCC marker CCER2 was strongly expressed in the tumor, while epidermal MCC-associated genes, such as S100A2 and CALML3/5, were largely absent in MCC cells, but highly expressed in the epidermis." (PMID 41131107, 2025). "Visualizing the mRNA expressions of CCER2 and PERP in spatial coordinates, we observed that the co-expression of these genes was more common in the epidermal compartment compared to the tumor core." (PMID 41131107, 2025). "Cells lacking expression of the tumor marker gene CCER2 expression were excluded to ensure that the analyzed cells comprised tumor cells rather than keratinocytes." (PMID 41131107, 2025).